PRRC2A (proline rich coiled-coil 2A)
Description:
May play a role in the regulation of pre-mRNA splicing.
Synonyms: BAT2; G2; D6S51E; D6S51
Tractability: Antibody: its Gene Ontology location is reachable by antibodies, with high confidence. PROTAC: ubiquitination databases record sites on it; its protein half-life has been measured.
Safety:
Unwanted effects reported when the protein is acted on. In parentheses: how it was acted on, where the effect was seen, and who reports it.
thrombocytopenia (source: ClinPGx)
Gene: Protein-coding gene on chromosome 6 (31,620,715 to 31,637,771, forward strand). Ensembl gene ENSG00000204469.
Subcellular location: Cytoplasm; Nucleus
Subcellular location (Human Protein Atlas): Cytosol; Nucleoplasm; Plasma membrane
Gene Ontology:
Molecular function: protein binding; RNA binding
Biological process: cell differentiation
Cellular component: cytosol; extracellular exosome; membrane; nucleoplasm; cytoplasm; nucleus
Genetic constraint (gnomAD): Loss-of-function variants: 57 observed, 220.68 expected, observed/expected ratio (o/e) 0.26, 90% interval 0.21 to 0.32. The upper end of that interval is the gene's LOEUF score, 0.32, which puts it in group 1 of 6, group 1 being the genes least tolerant of losing a copy. Missense variants: 3,075 observed, 2,929 expected, observed/expected ratio (o/e) 1.05, 90% interval 1.02 to 1.08. Synonymous variants: 1,191 observed, 1,126.3 expected, observed/expected ratio (o/e) 1.06, 90% interval 1.01 to 1.11.
Homologues: Orthologues: chimpanzee PRRC2A (99% identical), macaque PRRC2A (98% identical), pig PRRC2A (92% identical), rabbit PRRC2A (92% identical), dog PRRC2A (91% identical), mouse Prrc2a (90% identical), rat Prrc2a (89% identical), guinea pig PRRC2A (72% identical), tropical clawed frog prrc2a (44% identical), zebrafish prrc2a (35% identical), Caenorhabditis elegans F52G3.1 (11% identical). Paralogues in human: PRRC2C (33% identical), PRRC2B (28% identical).
Diseases named in the same sentence as PRRC2A in open-access papers:
PRRC2A is named in the same sentence as 47 diseases in open-access papers, as found by Europe PMC text mining. Sharing a sentence is not in itself a finding about the gene and the disease. The quoted sentences say what the papers report.
type 1 diabetes (7 papers, 2014 to 2024). "Several reports have shown that microsatellite repeats and missense polymorphisms in the PRRC2A gene conferred increased risk in various immune-related diseases, including type 1 diabetes, rheumatoid arthritis, coeliac disease, lupus nephritis." (PMID 35784577, 2022). "Nonetheless, recent studies have associated variants of the gene PRRC2A with obesity and type 1 diabetes risk." (PMID 36555722, 2022). "We also identified six patients (17.6%) with predicted deleterious variants in PRRC2A (p.R804C, p.R1556W, p.R1397W, p.F2083S) a gene associated with type 1 diabetes and rheumatoid arthritis, suggesting a function in immune regulation." (PMID 26122175, 2015). "The PRRC2A gene was responsible for the development of insulin-dependent diabetes mellitus." (PMID 35889263, 2022).
Obesity (6 papers, 2014 to 2025). Accumulation of substantial excess body fat. "In parallel, we used targeted methylation sequencing to fine map obesity-associated DNA methylation changes in the regulatory regions flanking the sentinel sites at PRRC2A, LIMD2 and 69 additional loci (N = 43 subcutaneous and N = 46 visceral adipocyte samples)." (PMID 37188674, 2023). "We focused on the PRRC2A gene which was linked to central adiposity, insulin resistance and T2D, and the LIMD2 gene which was linked to obesity, central adiposity and T2D." (PMID 37188674, 2023). "In addition to being related to the inflammatory processes of obesity and diabetes, PRRC2A is involved in neuromyelitis optica spectrum disorder." (PMID 40386807, 2025). "As the sites of methylation changes were distal to the PRRC2A and LIMD2 promoters, we used CRISPR-activation to assess whether the regulatory elements harbouring obesity-associated methylation changes were involved in target gene transcription." (PMID 37188674, 2023).
autoimmune disease (3 papers, 2022 to 2024). A disorder resulting from loss of function or tissue destruction of an organ or multiple organs, arising from humoral or cellular immune responses of the individual to their own tissue constituents. "Thus, these PRRC2A variants may provide insight into the pathogenesis of dysregulated m6A modification in autoimmune diseases." (PMID 35784577, 2022). "Six genes in the MHC Class III region, DDX39B, DXO, LSM2, NELFE, PRRC2A, and SKIV2L, encode RBPs and have a well-defined role in post-transcriptional gene regulation and RNA monitoring, and these genes may have important functions in immunity and be associated with autoimmune diseases." (PMID 38770048, 2024).
celiac disease (3 papers, 2005 to 2022). An autoimmune genetic disorder with an unknown pattern of inheritance that primarily affects the digestive tract. "Given that individuals with celiac disease are at elevated risk of non-Hodgkin's lymphoma (NHL), it is intriguing that variants within PRRC2A are also associated with NHL." (PMID 28282431, 2017). "The strongest independent CD interaction signal corresponded to genes in the HLA class III region, in particular PRRC2A and GPANK1/C6orf47, which are known to contain variants for non-Hodgkin's lymphoma and early menopause, co-morbidities of celiac disease." (PMID 28282431, 2017).
non-Hodgkin lymphoma (3 papers, 2017 to 2023). Distinct from Hodgkin lymphoma both morphologically and biologically, non-Hodgkin lymphoma (NHL) is characterized by the absence of Reed-Sternberg cells, can occur at any age, and usually presents as a localized or generalized lymphadenopathy associated with fever and weight loss. "In this context, several studies have demonstrated that there is a relationship between PRRC2A and several kinds of human cancers, such as hepatocellular carcinoma and non-Hodgkin lymphoma." (PMID 37686578, 2023).
type 2 diabetes (3 papers, 2014 to 2022). "In both type 2 diabetes and atherosclerosis, the protein PRRC2A was found to be present." (PMID 35889263, 2022).
glioblastoma (2 papers, 2020). The most malignant astrocytic tumor (WHO grade IV). "Thus, Prrc2a “reading” of OLIG2 mRNA (and its demethylation by FTO) might be relevant in the context of glioblastoma too." (PMID 32316617, 2020).
Insulin resistance (2 papers, 2014 to 2023). Increased resistance towards insulin, that is, diminished effectiveness of insulin in reducing blood glucose levels. "Overall, our integrative genomic and adipocyte functional studies are consistent with lower methylation levels at cg15809217 in obese subcutaneous adipocytes promoting insulin resistance and T2D, through reduced PRRC2A expression and impaired adipogenesis." (PMID 37188674, 2023).
Autoimmunity (1 paper, 2022). The occurrence of an immune reaction against the organism's own cells or tissues. "It indicates that PRRC2A risk variants might regulate autoimmunity and have the potential to be biomarkers of T1D progression." (PMID 35784577, 2022).
colon cancer (1 paper, 2025). "Consistently, upregulation of PRRC2A was also observed in colon tumors from the azoxymethane‐dextran sulfate sodium (AOM‐DSS) mouse model." (PMID 39582289, 2025). "In agreement, Prrc2a deletion led to the reduction in the RNA and protein levels of CK1ε in AOM‐DSS‐induced colon tumors and Apc mutation‐driven colorectal tumors." (PMID 39582289, 2025). "Knockdown of PRRC2A with siRNA abrogated proliferation and migration of colon cancer cells." (PMID 39582289, 2025). "Together, these findings demonstrated that Prrc2a was upregulated in CRC and promoted colon tumor progression." (PMID 39582289, 2025).
colorectal adenoma (1 paper, 2025). An adenoma that arises from the colon or rectum. "Considering that Prrc2a functions as a m6A reader protein, we performed m6A methylated RNA immunoprecipitation followed by sequencing (MeRIP‐seq; including input and immunoprecipitated samples) on tumor samples from Ctrl (n = 4) and cKO (n = 4) mice with AOM‐DSS‐induced colorectal adenoma." (PMID 39582289, 2025).
colorectal cancer (1 paper, 2025). A primary or metastatic malignant neoplasm that affects the colon or rectum. "m6A reader PRRC2A is aberrantly upregulated in colorectal cancer and associated with poor survival." (PMID 39582289, 2025). "In conclusion, we delineated a novel mechanism by which m6A reader protein PRRC2A promotes colorectal cancer progression." (PMID 39582289, 2025). "In summary, the work reveals a novel mechanism by which m6A reader PRRC2A promotes colorectal cancer progression via CK1ε and aberrant upregulation of WNT and YAP signaling." (PMID 39582289, 2025). "Elevated PRRC2A promotes colorectal cancer progression by enhancing the stemness and migrative capacity of cancer cells." (PMID 39582289, 2025). "Consistently, western blotting analysis showed PRRC2A elevation in multiple human colorectal cancer cell lines (HCT116, HT29, LoVo, and SW480), compared to normal colon epithelial cell line NCM460." (PMID 39582289, 2025).
colorectal tumors (1 paper, 2025). "Immunohistochemical results revealed consistent upregulation of PRRC2A protein in all stages of colorectal tumors." (PMID 39582289, 2025).
Coronary arteriosclerosis (1 paper, 2024). "Coronary arteriosclerosis shared 10 GWS genes with AD (BAG6, C6orf10, HLA-DQB1, HLA-DRA, HLA-DRB1, NDUFAF6, NME7, PLCG2, PRRC2A, and TRIB1), while myocardial infarction shared three genes with AD (HLA-DRA, PHB, and RP11-81K2.1)." (PMID 39201500, 2024).
intestinal tumors (1 paper, 2025). "Compared to the control group, the protein levels of CD133 and Lgr5 were significantly reduced in Prrc2a‐deficient intestinal tumors." (PMID 39582289, 2025).
leukemia (1 paper, 2024). A malignant (clonal) hematologic disorder, involving hematopoietic stem cells and characterized by the presence of primitive or atypical myeloid or lymphoid cells in the bone marrow and the blood. "Also, the functions of the newly identified m6A reader proteins, such as PRRC2A/B and FXR1, in the context of leukemia remain largely unexplored." (PMID 39085650, 2024).
prostate tumors (1 paper, 2021). "Seven regulators, including IGF2BP2, METTL3, METTL16, ZNF217, ZC3H13, RBM15B, and PRRC2A, exhibited significant correlations between CNVs and gene expression levels in prostate tumors." (PMID 34899855, 2021).
rheumatic diseases (1 paper, 2025). "It has been discovered that some of these genes (C2, BX511262.2, PRRC2A, BAG6, PBX2, GPSM3, NELFE and AIF1) are significant genetic targets shared by MetS and multiple rheumatic diseases." (PMID 39789419, 2025).
schizophrenia (1 paper, 2025). A major psychotic disorder characterized by abnormalities in the perception or expression of reality. "The microglial H-MAGMA-risk genes BAG6, NEU1, PRRC2A, PSMB8, PSMB8-AS1 and PSMB9 were associated with MS, ALS and schizophrenia." (PMID 40202986, 2025).
viral infection (1 paper, 2019). "Some proximal genes targeted by these 6 REs (FSCN1, GSTP1, JAM3, CHRNA6, NFAT5, and PRRC2A) are related to immune response, viral infection, and/or HCC based on ontological analysis." (PMID 31639042, 2019).
cancer (11 papers, 2019 to 2025). A tumor composed of atypical neoplastic, often pleomorphic cells that invade other tissues. "Mutations in PRRC2A are associated with multiple cancers, including non-Hodgkin-Lymphoma, lung cancer, ER-positive breast cancer and hepatocellular carcinoma, where they promote progression and immune infiltration." (PMID 36869665, 2023). "ZC3H13, VIRMA, and PRRC2A almost have a higher mutation frequency rate in all cancer types." (PMID 39457524, 2024). "Since high tumor ATF4 activity strongly correlates with poor cancer prognosis, this could explain in part why PRRC2A is associated to cancer." (PMID 36869665, 2023). "Expression levels of cancer stem cell (CSC) marker genes Lgr5, Smoc2, Axin2, Rnf43, and CD44 were markedly reduced in Prrc2a‐deficient tumors induced by AOM‐DSS treatment." (PMID 39582289, 2025). "PRRC2A is a protein involved in RNA metabolism and protein translation initiation, frequently upregulated in various cancers." (PMID 41373651, 2025). "This work identified m6A reader PRRC2A as an oncoprotein retaining cancer cell stemness and proliferation, revealing a unique mechanism for concurring WNT and YAP activation in CRC." (PMID 39582289, 2025). "Specifically, we observed that depletion of PRRC2A diminished the expression of cancer stem cell markers and stemness in both chemical and genetic CRC models, as well as in cancer cell lines and organoids." (PMID 39582289, 2025). "Another striking finding is that PRRC2A directly targets CK1ε, which promotes cancer progression by simultaneously increasing WNT and YAP activity." (PMID 39582289, 2025). "When the genomic alterations are investigated, most of the m6A regulators harbor SNVs across different cancers, with ZC3H13, VIRMA, and PRRC2A having higher mutation frequencies." (PMID 39457524, 2024). "Most of the m6A regulators are found to be mutated across the cancers, with ZC3H13, VIRMA, and PRRC2A having a higher frequency rate." (PMID 39457524, 2024). "The results showed that the expression of PRRC2A in metastatic lymph node was significantly greater than in primary carcinoma." (PMID 32292503, 2020). "More importantly, depletion of PRRC2A or CSNK1E suppressed the stemness of cancer cells and tumor growth, suggesting that this regulatory machinery could be of therapeutic interest for CRC." (PMID 39582289, 2025). "Importantly, the PRRC2A copy number was amplified in metastatic tumor tissues compared with paired primary cancer tissues and positively correlated with circPRRC2A expression (R2 = 0.5173, P = 0.012)." (PMID 32292503, 2020).
tumor (7 papers, 2020 to 2025). "Similarly, loss of Prrc2a in Vil‐Cre;Apcfl/+ mice also diminished the stemness of tumor cells and stimulated their differentiation." (PMID 39582289, 2025). "After AOM and DSS treatment, WT mice robustly developed multiple neoplasms in their colons, while Prrc2a deletion resulted in marked reductions in tumor burden, quantified by their size and number." (PMID 39582289, 2025). "In agreement with the importance of PRRC2A in maintaining tumor stemness, we found that Prrc2a deletion significantly repressed the organoid formation frequency and organoid growth of cultured intestinal and colonic crypts." (PMID 39582289, 2025). "Many of the m6A regulators have a high SNV mutation frequency in most tumor types, especially in UCEC, SKCM, COAD, and STAD, furthermore, ZC3H3 in UCEC and PRRC2A in SKCM are the top two whose mutation frequency is above 50%." (PMID 39457524, 2024). "Furthermore, in vitro limiting dilution assay showed that the knockdown of PRRC2A markedly suppressed tumor spheroid formation ability of HCT116 cells." (PMID 39582289, 2025). "Furthermore, tumor xenograft assay also demonstrated that CSNK1E overexpression reversed the inhibitory effect of PRRC2A knockdown on tumor growth." (PMID 39582289, 2025). "In addition, the m6A readers, including YTHDF1/2/3, HNRNPC, HNRNPA2B1, RBMX, PRRC2A, and CPSF6, also demonstrated a higher expression in the tumor samples compared to the normal tissues." (PMID 38610981, 2024). "circ-PRRC2A acts as a sponge molecule, adsorbing miR-514a-5p and miR-6776-5p to prevent the degradation of the tissue-specific oncogene TRPM3 mRNA, and promote angiogenesis and tumor metastasis." (PMID 34616746, 2021).
infection (1 paper, 2019). The state of being infected such as from the introduction of a foreign agent such as serum, vaccine, antigenic substance or organism. "Expectedly, in the very early stages of infection, proteins involved in translation, transcription and DNA condensation were upregulated, notably HIST1H1E, HNRNPL, PRRC2A and TRIM28." (PMID 31315557, 2019).
PRRC2A also shares sentences with these, for which no sentence is quoted: insulin-dependent diabetes mellitus (4 papers); rheumatoid arthritis (3); atherosclerosis (2); breast carcinoma (2); malaria (2); cardiovascular disease (1); colitis (1); Colon (1); End-Stage Renal Failure (1); hepatocellular carcinoma (1); inflammatory bowel disease (1); influenza (1); iridocyclitis (1); liver cancer (1); lung carcinoma (1); lupus nephritis (1); myocardial infarction (1); neuromyelitis optica spectrum disorder (1); ovarian carcinoma (1); Polycystic kidney (1); prostate carcinoma (1); psoriasis (1); renal cell carcinoma (1); smallpox (1).